PHF8 (PHD finger protein 8)
Diseases named in the same sentence as PHF8 in open-access papers (continued):
Sharing a sentence is not in itself a finding about the gene and the disease.
cancer (continued). "While PHF8 is well characterized as a transcriptional activator, our current studies suggest that PHF8 may also contribute to transcriptional repression, thereby promoting cancer progression." (PMID 41198671, 2025). "Therefore, PHF8 has been suggested as a tumor marker and therapeutic target for human cancer." (PMID 36980457, 2023). "However, despite this variable expression pattern, a higher expression of PAK4 and PHF8 might be used as a prognostic indicator for cancer patients." (PMID 36980457, 2023). "Therefore, subcellular localization of the expression of PAK4 and PHF8 might be different according to the type of cancer and biological status of cancer cells." (PMID 36980457, 2023). "To further investigate the clinical relevance of the HER3/miR-34b-5p/PHF8 axis, we analyzed the expression correlations between miR-34b-5p and PHF8 or HER3 using the TCGA pan-cancer dataset." (PMID 41198671, 2025). "PHF8 induces EMT-like cell status through upregulating key EMT transcription factors SNAI1 and ZEB1, thus contributing to cancer cell growth and metastasis." (PMID 39311138, 2024). "Plant homeodomain finger protein 8 (PHF8) is a histone demethylase and shown to be involved in cell growth, survival, apoptosis, and the epithelial to mesenchymal transition (EMT) of cancer cells." (PMID 36980457, 2023). "The importance of PAK4 and PHF8 in cancer progression and as therapeutic targets has been emphasized in various human cancers, and the inhibition of PAK4 and PHF8 is under evaluation in cancer therapy." (PMID 36980457, 2023). "The histone demethylase PHD-finger protein 8 (PHF8) is upregulated in PCa, acts as a transcriptional coactivator of AR via H4K20 demethylation and promotes cancer cell proliferation, migration, invasion, and neuroendocrine differentiation." (PMID 35205419, 2022). "By using different model systems including combined Phf8 knockout and the TRAMP mouse model, NEPC cell lines, NEPC PDX and patients' cancer tissues, we established the PHF8/FOXA2 axis and illustrated its role in NEPC development." (PMID 33009820, 2021). "The previous findings and our current data suggest that some soluble factors from cancer cells can activate the p38/JNK pathway, resulting in CCL7 overexpression via transcriptional regulation by PHF8 in macrophages." (PMID 34206004, 2021). "The dissociation of PHF8 from TopBP1 presents a potential strategy for developing novel cancer therapies targeting TopBP1." (PMID 41198671, 2025). "Collectively, PHF8 transcriptionally regulates multiple target genes and facilitates the activation of oncogenic signaling networks, including Wnt/β-catenin, MER/ERK, PI3K–AKT, and TGF-β signaling, thereby aiding in cancer initiation and progression." (PMID 39311138, 2024). "Concerning histone demethylases, Jumonji C domain KDMs members of family GASC1/KDM4C and JMJD1C/KDM3C demethylating agents of repressive histone marker H3K9 and KDM7B/PHF8 which specifically demethylate H3K27me1/2, play a critical role in ESCC cancer development." (PMID 31739546, 2019). "A significant negative correlation between miR-34b-5p and PHF8 was observed in several cancer types, suggesting that PHF8 may be a potential target of miR-34b-5p." (PMID 41198671, 2025).
tumor (24 papers, 2013 to 2025). "n-PHF8 positivity was significantly associated with the T category of tumor stage, higher histologic grade, and the expression of c-PHF8." (PMID 36980457, 2023). "PHF8 loss promotes the development of an anti-tumor immune memory, inflames immunologically-cold tumors, and sensitizes ICB-based immunotherapy." (PMID 37454216, 2023). "High expression of PHF8 was significantly associated with vascular invasion, large tumor size, poor tumor differentiation and advanced tumor stage." (PMID 30180906, 2018). "Combining univariate- and multivariate- analysis revealed that PHF8 upregulation, vascular invasion and advanced tumor stage were the independent risk factors for predicting poor OS and RFS." (PMID 30180906, 2018). "In addition, the tumor-immune correlation analysis demonstrated that PHF8 expression was strongly negatively associated with the levels of MHC class I genes including B2M, HLA-A/B/C, TAP1/2 as well as chemokines such as CCL5 and CXCL10." (PMID 40001243, 2025). "A regulator of SETDB1 maintenance, PHF8, has been identified as a mediator of tumor immune escape; its ablation stimulates antiviral mimicry in colorectal cancer cells, resulting in the inhibition of tumor growth and immune susceptibility." (PMID 39205286, 2024). "In summary, these results substantiate that PHF8 loss induces potent anti-tumor immunity." (PMID 37454216, 2023). "This promoted us to speculate that PHF8 loss might induce an anti-tumor immune memory." (PMID 37454216, 2023). "In contrast, PHF8 knockdown significantly delayed tumor growth and reduced tumor weight and the proportion of Ki-67-positive cells." (PMID 40001243, 2025). "High expression of PD-L1 in tumor tissue has been shown to impair the immune response in vivo, while PHF8 as a transcription coactivator is highly expressed in a variety of tumor types." (PMID 40001243, 2025). "To verify the role of PHF8 in regulating the immune response, we established allograft tumor models by injecting PHF8-knockdown MC38 cells and control cells into the inguinal region of C57BL/6 mice and divided them into two groups, respectively." (PMID 40001243, 2025). "Consistently, measurements of tumor weight and bioluminescence imaging of the tumors confirmed that overexpression of PHF8 restored tumor growth in HER3-depleted TNBC cells." (PMID 41198671, 2025). "The results showed that ectopic expression of PHF8 dramatically accelerated tumor growth and increased tumor weight compared to the control." (PMID 40001243, 2025). "PHF8 knockdown synergizes with anti-PD1 treatment to suppress tumor growth by down-regulating the levels of PD-L1." (PMID 40001243, 2025). "PHF8 has been shown to be highly expressed in BC tumors compared to normal breast tissues and other tumor types." (PMID 41198671, 2025). "The review delves into the oncogenic potential of certain PHD finger proteins, exemplified by PHF1 and PHF8, which promote tumor progression through epigenetic dysregulation and modulation of signaling pathways like Wnt and TGFβ." (PMID 38813086, 2024). "Specifically, the PHF8-IL-6 axis influences trastuzumab resistance and T-cell infiltration, highlighting its role in tumor immunity and therapy resistance." (PMID 38813086, 2024). "Immunohistochemical expression of PAK4 and PHF8 was observed in both the nuclei and cytoplasm of tumor cells in human GBC tissue." (PMID 36980457, 2023). "Overall, our study establishes PHF8 as an epigenetic checkpoint, and targeting PHF8 is a promising viral mimicry-inducing approach to enhance intrinsic anti-tumor immunity or to conquer immune resistance." (PMID 37454216, 2023). "Intriguingly, Phf8 wild-type 4T1 tumors grew much slower in rechallenged hosts inoculated with CT26 Phf8-KO tumors, indicating an anti-tumor immune memory." (PMID 37454216, 2023). "We injected lethal doses of wild-type tumor cells with intact Phf8 into mice that had already rejected Phf8-KO tumors." (PMID 37454216, 2023).
tumor (continued). "Accordingly, ectopic expression of Phf8 accelerated tumor growth and reduced survival in immunocompetent mice." (PMID 37454216, 2023). "In GBCs, the expression of PAK4 and PHF8 was observed in both the nuclei and cytoplasm of tumor cells." (PMID 36980457, 2023). "Collectively, these data suggest that Phf8 depletion activates anti-tumor immunity by triggering interferon and antiviral responses." (PMID 37454216, 2023). "In the context of HCC, BBOX1-AS1 has been shown to promote tumor progression, autophagy, and drug resistance by upregulating a protein known as PHF8." (PMID 37925403, 2023). "Taken together, these results suggest that tumor PHF8 is critical for intrinsic resistance to spontaneous and immunotherapy-induced tumor immunity." (PMID 37454216, 2023). "Taken together, our results reveal that BBOX1-AS1 promotes tumor progression and sorafenib resistance by regulating miR-361-3p/PHF8, indicating new therapeutic strategies for the treatment of HCC." (PMID 36699616, 2022). "Mechanistically, BBOX1-AS1 enhanced the stability of PHF8 mRNA by targeting the PHF8 inhibitor miR-361-3p to regulate tumor progression and autophagy in HCC." (PMID 36699616, 2022). "To further investigate the effect of PHF8 on NEPC development, we conducted RNA‐seq on tumor tissues derived from Phf8‐KO and control TRAMP mice (data deposited in GSE157621)." (PMID 33009820, 2021). "In vivo experiment proved that PHF8-silencing exhibited the slower tumor growth, smaller tumor size and less lung metastases compared with control group, indicating that PHF8-silencing blocked tumorigenesis and metastasis." (PMID 30180906, 2018). "Taken together, PHF8 was able to promote tumorigenesis, tumor growth, EMT, migration, invasion and metastasis of HCC cells." (PMID 30180906, 2018). "More attention has been paid to the roles of PHF8 in promoting tumor metastasis and EMT by co-transcriptionally activating SNAI1 and VIM expression, which was consistent with the current results." (PMID 30180906, 2018). "In this study, we reported oncogenic roles of PHF8 in clinical significance and promotion to tumor development, EMT and metastasis in HCC." (PMID 30180906, 2018). "In accordance, our data showed that PHF8 positively regulated tumor proliferation, migration, invasion and metastasis of HCC cells in vitro and in vivo." (PMID 30180906, 2018). "Knockdown persistence to the end of the experiment was verified by real-time quantitative PCR and western blot analyses of PHF8 expression in tumor tissues." (PMID 24146981, 2013). "Future studies should focus on the molecular mechanisms of PHF8-induced ESCC tumor development and progression as well as on strategies to downregulate this important epigenetic protein or inhibit its function for a potential therapeutic strategy in ESCC." (PMID 24146981, 2013). "However, ectopic expression of PHF8 at least partially rescued tumor growth-inhibited by HER3 depletion." (PMID 41198671, 2025). "Furthermore, orthotopic xenograft models revealed that enforced PHF8 expression restored tumor growth suppressed by HER3 silencing in vivo." (PMID 41198671, 2025). "Given that epithelial-mesenchymal transition (EMT) and matrix metalloproteinases (MMPs) play crucial roles in the process of tumor metastasis, we next examined the effect of PHF8 overexpression or knockdown on the expression of several EMT-related genes and MMPs." (PMID 40001243, 2025). "This is explained by PHF8 interaction with c-Jun and removal of H3K9me2 methylation to activate PRKCA (coding PKCα) and promote SRC-induced degradation of PTEN, a tumor suppressor commonly mutated in tumors and whose dysfunction is key to activate PI3K–AKT signaling." (PMID 39311138, 2024). "Notably, in contrast to Phf8 wild-type counterparts, Phf8-KO tumor cells were completely rejected in syngeneic immunocompetent mice." (PMID 37454216, 2023).
tumor (continued). "We observed that Phf8 knockout potently inhibited tumor formation in immunocompetent mice, and those mice could remain long-term tumor-free." (PMID 37454216, 2023). "The role of PHD finger protein 8 (PHF8) in anti-tumour immunity remains to be investigated." (PMID 37454216, 2023). "Our observations of enhanced tumor cell immunogenicity and increased CD8+ T cell immune responses caused by Phf8 depletion suggest that Phf8-deficient tumors may be susceptible to ICB therapy." (PMID 37454216, 2023). "As molecular events in PHF8-mediated anti-tumor immunity, type 1 interferons and interferon-stimulated genes (ISGs) were significantly upregulated after Phf8 loss in CT26 and MC38 cells, whereas Phf8 reintroduction could block this effect." (PMID 37454216, 2023). "This prompted us to explore the role of PHF8 in tumor immune evasion." (PMID 37454216, 2023). "The functional rescue experiments showed that PHF8 acted as a key factor in regulating the biological effects induced by BBOX1-AS1 and miR-361-3p in HCC, indicating that BBOX1-AS1 promotes tumor progression and sorafenib resistance by regulating miR-361-3p/PHF8." (PMID 36699616, 2022). "In this study, we for the revealed that BBOX1-AS1 could promote tumor progression, autophagy, and drug resistance by upregulating PHF8 in HCC." (PMID 36699616, 2022). "This study revealed that BBOX1-AS1 could promote tumor progression, autophagy, and drug resistance by upregulating PHF8 in HCC cells." (PMID 36699616, 2022). "Xenograft of HepG2 tumor transfected with miR‐383 mimics significantly decreased the growth of HepG2 tumors compared with those transfected with miR‐con, and ectopic overexpression of PHF8 in HepG2 tumors alleviate the inhibition of miR‐383 mimics." (PMID 32441881, 2020). "As a transmembrane protein that regulates cell adhesion and tumor metastasis, E-cadherin could be suppressed by PHF8 upregulation in other tumors." (PMID 30180906, 2018). "Our findings provided a novel insight into function of PHF8 on tumor progression and metastasis, and suggested that PHF8 blockage might be a promising therapeutic approach for HCC." (PMID 30180906, 2018). "Moreover, IHC analysis of tumor sections revealed a marked reduction of PHF8 expression in HER3-depleted tumors, accompanied by a significant decrease of Ki67 and increase of cleaved caspase-3, indicative of reduced proliferation and enhanced apoptosis, respectively." (PMID 41198671, 2025). "The analysis of tumor-immune interaction further showed that the expression of PHF8 in CRCs was inversely connected with multiple immune infiltrating lymphocytes, suggesting that PHF8 may hinder the immune response process of the tumor." (PMID 40001243, 2025). "Loss- and gain-of-function approaches demonstrate that PHF8 promotes cell invasion without affecting proliferation in vitro and increases dissemination but not subcutaneous tumor growth in vivo, thus supporting its specific contribution to the acquisition of metastatic potential." (PMID 35179962, 2022). "To evaluate the functional significance of PHF8 in HER3-driven TNBC tumor growth in vivo, we conducted experiments with orthotopic tumor xenograft models." (PMID 41198671, 2025). "This was supported by the results in PHF8 inhibitor daminozide-treated human- and murine-derived CRC cells as well as daminozide-treated allograft tumor tissues." (PMID 40001243, 2025). "The results showed that both PHF8 knockdown and PD1 antibody slowed tumor growth and reduced tumor weight compared to the control, while PHF8 knockdown further enhanced the efficacy of PD1 antibody." (PMID 40001243, 2025). "In this study, we uncovered a previously unrecognized HER3/miR-34b-5p/PHF8 signaling axis that drives TNBC cell proliferation and tumor growth." (PMID 41198671, 2025). "Immunohistochemical analysis of tumor samples revealed that 35.2% (32/91) of them exhibited high HER3 expression, while 45.1% (41/91) of them showed high PHF8 expression." (PMID 41198671, 2025).
tumor (continued). "In summary, our findings suggest that PHF8 facilitates SETDB1 stabilization to establish H3K9me3 marks on heterochromatin, leading to retrotransposon silencing and tumor immune evasion." (PMID 37454216, 2023). "To determine how PHF8 suppresses anti-tumor immunity, we performed transcriptomic analysis (GSE212779) of Phf8 wild-type, KO and Phf8 reconstitution (Phf8 KO + Phf8) CT26 tumor cells." (PMID 37454216, 2023). "Further biochemical and cellular experiments are needed to clarify how PHF8 maintains the stability of nuclear SETDB1 and further regulates its dynamic activity in tumor cells." (PMID 37454216, 2023). "Multivariate analysis indicated that the age, tumor stage, the T category of the stage, n-PAK4 expression, and n-PHF8 expression were independent predictors of OS and RFS in GBC patients." (PMID 36980457, 2023). "The elevated PHF8 expression, facilitated by BBOX1-AS1, contributes to tumor progression and increased autophagy levels in HCC cells." (PMID 37925403, 2023). "The relative expression of BBOX1-AS1 and PHF8 in four groups’ tumor samples demonstrated that BBOX1-AS1 knockdown effectively interfered with the promotion of BBOX1-AS1 and PHF8 induced by sorafenib." (PMID 36699616, 2022). "Our results demonstrated many oncogenic features of PHF8 in ESCC, including inhibition of ESCC cell apoptosis as well as promotion of ESCC cell proliferation in vitro and tumor growth in vivo." (PMID 24146981, 2013). "In this study, we investigated the role of PHF8 in ESCC and found that PHF8 has many oncogenic features including promotion of ESCC cell proliferation and tumor growth as well as ESCC cell migration and invasion abilities." (PMID 24146981, 2013). "We also found that PHF8 promoted ESCC cell migration and invasion, indicative of the potential involvement of PHF8 in promotion of tumor metastasis." (PMID 24146981, 2013). "Mechanistically, HER3 activation suppresses the tumor-suppressive microRNA miR-34b-5p, resulting in the upregulation of the histone demethylase PHF8 (KDM7B), which in turn represses the expression of the CDK inhibitor p27Kip1 and facilitates G1–S cell cycle progression." (PMID 41198671, 2025). "Within the tumor microenvironment, IL-6 facilitates the infiltration of inflammation-induced CD8+ T cells and cell-based models of NED and CRPC have been induced by IL-6 treatment in which PHF8 was found to be downregulated during NED and upregulated in CRPC." (PMID 39311138, 2024). "Our rescue results from the catalytically inactive mutant (Phf8H247A) showed that PHF8 in silencing retrotransposon and a viral mimicry response and even in tumor immune evasion was independent of its catalytic activity." (PMID 37454216, 2023). "Additionally, CCK8, xenograft tumor model, trans‐well assay and tandem mCherry‐GFP‐LC3 fusion protein assay showed that knockdown of PHF8 significantly inhibited HCC cells growth, migration, invasion, and autophagy." (PMID 32441881, 2020). "Moreover, the immunofluorescence density of granzyme B+ (GZMB+) and interferon-γ+ (IFN-γ+) CD8+ T cells also significantly increased in Phf8-deficient CT26 tumors, implying that depletion of tumor PHF8 promotes adaptive anti-tumor CD8+T cell immune responses and results in tumor growth repression." (PMID 37454216, 2023). "However, the function and mechanism of tumor PHF8 in anti-tumor immunity have not yet been elucidated." (PMID 37454216, 2023). "Moreover, genetic knockout Phf8 resulted in comparable tumor progression in immunodeficient Rag2-/- mice that do not have mature T and B cells." (PMID 37454216, 2023). "Notably, this PHF8 catalytically inactive form possessed comparable tumor promoting ability with the wild-type PHF8, further indicating that the role of PHF8 in tumor immune evasion was independent of its catalytic activity." (PMID 37454216, 2023). "However, PHF8 occupancy and its downstream transcriptional programs in those tumor types have not been elucidated." (PMID 35179962, 2022).